EPCAM (epithelial cell adhesion molecule)
Diseases named in the same sentence as EPCAM in open-access papers (continued):
Sharing a sentence is not in itself a finding about the gene and the disease.
cancer (continued). "The antigen EPCAM is presently being used as a target for immunotherapy treatment of human carcinomas." (PMID 23938213, 2013). "Regulated intramembrane proteolysis (RIP) of human EpCAM was reported in carcinoma and HEK293 cells." (PMID 24009667, 2013). "EpCAM is expressed at low levels in a variety of normal human epithelial tissues, but is overexpressed in 70–90% of carcinomas." (PMID 23460885, 2013). "Regulated intramembrane proteolysis of EpCAM was first described in human carcinoma cells and after ectopic expression in HEK293 cells." (PMID 24009667, 2013). "Since the generally accepted definition of a CTC includes the expression of epithelial surface markers, such as EpCAM, if a cancer cell loses its epithelial surface markers (which is suggested in EMT), it will not be separated and/or identified as a CTC." (PMID 22844540, 2012). "Cancer immunotherapy by using a bispecific EpCAMXCD3 antibody to redirect the T lymphocytes to target the EpCAM-positive CSCs reduced cell proliferation." (PMID 23213278, 2012). "Chimeric EpCAM aptamer functionalized with groups such as locked nucleic acid using supraparamagnetic iron oxide nanoparticles showed efficacy in killing cancer cells." (PMID 23213278, 2012). "Flow cytometry was used to study the co-expression of EpCAM with putative cancer stem cell markers, such as CD44, CD24, and ABCG2, in RB primary tumors." (PMID 22328825, 2012). "We used this property of Dox for the study, by intercalating it to EpDT3 to deliver it to EpCAM-expressing cancer stem cells." (PMID 23213278, 2012). "We have therefore investigated the possibilities and limitations for EpCAM as possible molecular imaging target using a panel of preclinical cancer models." (PMID 22590529, 2012). "Recently, an RNA aptamer was isolated against the cancer stem cell marker EpCAM, by cell surface SELEX for proposed theranostic applications in EpCAM-positive cancer cells." (PMID 23213278, 2012). "Cancer cells with an epithelial phenotype use EpCAM overexpression and signaling for growth and invasion." (PMID 23110550, 2012). "Using flow cytometry, we studied the individual expression of EpCAM, CD44, CD24 and ABCG2 and also studied the co-expression of EpCAM with other three putative cancer stem cell markers." (PMID 22328825, 2012). "Having isolated the EpCAM+ cells from Y79 cells, we next determined their cancer stem-like cell properties." (PMID 22328825, 2012). "EpCAM was co-expressed with all cancer stem cell markers (CD44, CD24, and ABCG2) in primary RB tumors." (PMID 22328825, 2012). "An ‘ugly’ role of EpCAM is reflected by studies describing both a protective and a promoting role within the very same cancer type." (PMID 23110550, 2012). "Several studies for non-invasive monitoring of cancer cells in xenograft mouse models with EpCAM as target were published over the last 5 years." (PMID 22590529, 2012). "EpCAM is ideal for drug targeting in RB because as this molecule is overexpressed in invasive tumors and is a putative cancer stem cell marker." (PMID 23213278, 2012). "Our data demonstrate that EpCAMhigh cancer cells with epithelial morphology clearly benefit from EpCAM overexpression with regard to proliferation and capacity to invade host tissue." (PMID 23110550, 2012). "As EpCAM is a cancer stem cell marker, this aptamer-based targeted drug delivery will prevent the undesired effects of non-specific drug activity and will kill cancer stem cells precisely in RB." (PMID 23213278, 2012). "EpCAM aptamer–based drug delivery in the future can be potentially exploited with stable linking of the drugs for targeting EpCAM-positive cancer stem cells in RB as well as in other cancers." (PMID 23213278, 2012). "These antibodies bind to EpCAM and enhance the immunological response to EpCAM-positive cancer cells, either in blood or malignant ascites." (PMID 23110550, 2012).
cancer (continued). "In vitro methyl thiazol tetrazolium (MTT) assay, invasion assay, and neurosphere formation assay were performed to characterize EpCAM+ cells for their cancer stem/progenitor cell-like properties." (PMID 22328825, 2012). "The mRNA expression levels for EpCAM of twelve human cancer cell lines were analyzed in vitro by qPCR." (PMID 22590529, 2012). "While there are increasing reports about the role of EpCAM or TROP2 in various cancers, only a few reports of EpCAM or TROP2 expression in NSCLC have been published." (PMID 22482828, 2012). "During the organization of our data, we found several serological glycosylated proteins like ORM2, EpCAM changing in levels during cancer development." (PMID 22363757, 2012). "EpCAM localizes to the basolateral membrane in normal polarized epithelia, but in carcinoma this expression pattern changes to an intense uniform membranous overexpression that is frequently associated with cytoplasmic staining." (PMID 23110550, 2012). "They found CK- CTCs in about 23% of blood samples of 30 carcinoma patients but only 0.2% EpCAM- CTCs." (PMID 22646670, 2012). "The potential application of the cell microarray chip for the detection of CTCs was shown, thus demonstrating accurate detection by double staining for cytokeratin and EpCAM at the single carcinoma cell level." (PMID 22396762, 2012). "ADAM17 is also a sheddase for EpCAM, homophilic cell adhesion molecule, often highly expressed on carcinoma cells." (PMID 23251384, 2012). "Epithelial cell adhesion molecule expression differs between carcinomas with either a good or poor prognostic indication depending on the carcinoma." (PMID 22187035, 2012). "Recently, EpCAM also gained interest as a signal transducer and as a marker of cancer-initiating cells." (PMID 21694727, 2011). "A number of studies using CellSearch have shown a good correlation between the numbers of these circulating CK-positive/EpCAM-positive cells and prognosis for cancer survival." (PMID 21577258, 2011). "There is evidence for upregulation and down-regulation of EpCAM with cancer progression and metastasis, and it is likely that both are true, depending on the type and stage of cancer and other biological variables not yet well understood." (PMID 21577258, 2011). "Recently, EpCAM has attracted major interest as a target for antibody- and vaccine-based cancer immunotherapies." (PMID 21281469, 2011). "To confirm the impact of EpCAM on AP-1 target gene expression, we specifically ablated EpCAM and then analyzed more than 120 AP-1 target genes known to be involved in cancer invasion using quantitative RT-PCR." (PMID 22132731, 2011). "EpCAM expression in primary cancer specimens has been studied extensively, and a number of studies in the surgical pathology literature have evaluated the association between EpCAM expression and prognosis." (PMID 22132731, 2011). "A better understanding of the relation between EpCAM and cancer invasion will clearly facilitate the rational design, and successful application of molecular therapies targeting EpCAM in epithelial carcinomas." (PMID 22132731, 2011). "Although these studies are far from definitive, taken together, they do suggest a cancer type-specific role for EpCAM in cancer biology and invasion." (PMID 22132731, 2011). "TROP2 and EpCAM are expressed in normal epithelial tissues, while they are known as oncogene and promote cancer cell proliferation and migration." (PMID 22194864, 2011). "Despite this intense interest in EpCAM as a target for molecular therapy, there have been limited attempts to define the functional role of EpCAM in cancer biology." (PMID 22132731, 2011). "Cytokeratin and EpCAM antibodies are used as markers for the detection of blood-borne or disseminated cancer cells." (PMID 22140428, 2011). "EpCAM is overexpressed in the majority of epithelial carcinomas, and there are currently a number of different molecular therapies under development." (PMID 22132731, 2011).
cancer (continued). "The epithelial cell adhesion molecule (EpCAM) protein is commonly expressed on normal epithelial and overexpressed on malignant cells in a subset of human carcinomas." (PMID 21281486, 2011). "EpCAM is a cell-surface glycoprotein that is overexpressed in the majority of epithelial carcinomas." (PMID 22132731, 2011). "All patients with MPC and 17 out of 20 patients with MLC had primary carcinomas of glandular origin, usually expressing the EpCAM antigen." (PMID 21829190, 2011). "Proteolytic cleavage of the extracellular domain (EpEx) of Epithelial cell adhesion molecule (EpCAM) and nuclear signaling by its intracellular oncogenic domain Ep-ICD has recently been implicated in increased proliferation of cancer cells." (PMID 20579375, 2010). "Certain normal epithelial tissues and embryonic stem cells express EpCAM, but there is evidence to suggest that EpCAM on normal epithelial tissues is largely sequestered while it is accessible on the surface of cancer cells." (PMID 20976159, 2010). "EpCAM was recently shown to have oncogenic potential and nuclear signalling activity in cancer cells, and to induce upon overexpression the proliferation of quiescent cells via c-myc." (PMID 21044305, 2010). "EpCAM knockdown experiments in MCF-7 cells have shown that cells cease to proliferate, migrate and invade soft agar, indicating that this cancer cell line is dependent on EpCAM signalling." (PMID 21044305, 2010). "All antibodies induced lysis of EpCAM-expressing cancer cell lines by both ADCC and CDC with potencies that correlated with their binding affinities." (PMID 21044305, 2010). "DMR molecular profiling of Her2/neu, EGFR, and CD326 (EpCAM) cancer markers on mammalian cells was first demonstrated using the first-generation DMR device." (PMID 21977404, 2010). "The first monoclonal antibody ever tested in cancer patients was the EpCAM-specific murine IgG2a antibody 17-1A produced in ascites of mice." (PMID 21044305, 2010). "EpCAM has recently been described as a cancer stem cell marker expressed together with CD44, CD133, and CD166." (PMID 20976159, 2010). "In 2009, an anti-EpCAM trispecific antibody called catumaxomab (Removab) obtained market authorization in Europe for treatment of malignant ascites in cancer patients." (PMID 21044305, 2010). "All five anti-EpCAM mABs showed specific complement-mediated lysis of cancer cells in the range of 30-55% at an antibody concentration of 20 μg/ml." (PMID 21044305, 2010). "The clinical significance of Ep-ICD in human cancers needs to be determined in view of the multiple roles of EpCAM as an oncogenic signal transducer, cell adhesion molecule and cancer stem cell marker." (PMID 21152431, 2010). "Epithelial cell adhesion molecule (Ep-CAM) is a ubiquitous antigen in epithelial cells that is highly overexpressed in epithelial ovarian carcinoma as well as other cancers, and its expression is correlated with malignant proliferation." (PMID 20145720, 2009). "It is further important to note that the over-expression of EpCAM is part of the signature of cancer-initiating cells at least in human colon, breast, and pancreas carcinomas." (PMID 19925656, 2009). "Epithelial cell adhesion molecule EpCAM is a transmembrane glycoprotein, which is frequently over-expressed in simple epithelia, progenitors, embryonic and tissue stem cells, carcinoma and cancer-initiating cells." (PMID 19925656, 2009). "Eventually, EpCAM is reckoned as a potent oncogenic factor, which is activated via regulated intramembrane proteolysis and which plays an important role in cancer and stem cell signalling." (PMID 19925656, 2009). "EpCAM is expressed by embryonic stem cells and cancer stem cells, and it is possible that EpCAM influences trophoblast stem cell behavior." (PMID 20046825, 2009). "Owing to its mode of action and capacities, EpCAM was termed a "surface-to-nucleus missile" that is involved cancer and stem cells' signalling." (PMID 19925656, 2009).
cancer (continued). "Elevated EpCAM levels in transformed tissues are thought to promote cell proliferation, contributing to carcinoma progression." (PMID 19609345, 2009). "Certainly, the differential localisation of EpCAM in normal tissue (basolateral) versus carcinomas (homogenous distribution at the membrane) will further influence EpCAM interactions and activation." (PMID 19925656, 2009). "The high-level over-expression of EpCAM in a plethora of carcinomas led to the use of it as a marker with prognostic quality and as a target for therapeutic strategies." (PMID 19925656, 2009). "EpCAM is a well-established marker for carcinomas of epithelial origin and a potential target for immunotherapy." (PMID 19609345, 2009). "During later development and adulthood, EpCAM is largely dispensable, reinforcing its suitability as a target for anti-carcinoma immunotherapy with minimal side effects." (PMID 19609345, 2009). "A variety of cancer therapy strategies and clinical trials have since made use of EpCAM as a target molecule for (single-chain) monoclonal and bispecific antibodies." (PMID 19002182, 2008). "Owing to its immunogenic properties in cancer patients, active and passive immunotherapeutic agents against the EpCAM antigen have been developed." (PMID 18813308, 2008). "Expression of the epithelial cell adhesion molecule EpCAM is upregulated in a variety of carcinomas." (PMID 19002182, 2008). "Expression of EpCAM is known to be upregulated in a variety of carcinomas including those of the lung and colon." (PMID 19002182, 2008). "This meeting has provided major insights into the role of EpCAM in cancer, and ongoing research promises to broaden this understanding." (PMID 17211480, 2007). "Until we understand exactly how EpCAM antibodies on cancer cells, we cannot fully grasp what really happens in vivo and therefore we can only marginally improve EpCAM-based immunotherapy." (PMID 17325709, 2007). "In summary, catumaxomab and HO-3 exhibit a strong potency difference with regard to their ability to induce the killing of EpCAM-positive cancer cells in vitro." (PMID 17622246, 2007). "Epithelial cell adhesion molecule EpCAM is a transmembrane glycoprotein that is frequently overexpressed in a variety of carcinomas." (PMID 17622246, 2007). "Driven by the knowledge of differential glycosylation of EpCAM in normal vs carcinoma tissue, we assessed the dependence of HO-3 binding on the glycosylation status of the molecule." (PMID 17622246, 2007). "EpCAM is a pan-epithelial differentiation antigen expressed on the basolateral surface of all carcinomas to varying degrees." (PMID 17325709, 2007). "Inhibition of EpCAM expression with antisense mRNA reduces proliferation and metabolism in human carcinoma cells." (PMID 17325709, 2007). "Carcinomas and actively proliferating tissues show that increased and differential expression of EpCAM." (PMID 17325709, 2007). "The therapeutic potential for the inhibition of EpCAM was illustrated by a knockdown phenotype of EpCAM in carcinoma cells." (PMID 17622246, 2007). "The high frequency of its overexpression in a multitude of human carcinomas qualifies EpCAM as a target of interest for immunotherapy." (PMID 17622246, 2007). "Epithelial cell adhesion molecule is currently targeted by two principally different approaches in cancer therapy: passive and active immunotherapy." (PMID 16404366, 2006). "The Epithelial Cell Adhesion Molecule (EpCAM) is a type I transmembrane glycoprotein expressed by carcinomas of head and neck, ovary, colon, breast, kidney and lung." (PMID 17125516, 2006). "MT201 is a fully human monoclonal IgG1 antibody with moderate affinity for epithelial cell adhesion molecule (Ep-CAM) being clinically developed for the treatment of carcinomas." (PMID 15655555, 2005). "Epithelial cell adhesion molecule is overexpressed on the majority of human carcinomas, and frequently expressed de novo on squamous cell carcinoma of head and neck, bladder and lung." (PMID 15655555, 2005).
cancer (continued). "Furthermore, EpCAM inhibition decreased mesenchymal marker expression, reduced filopodia formation, and suppressed extravasation of cancer cells into the lung in an in vivo mouse model." (PMID 41785279, 2026). "The EpCAM is a 40 KD transmembrane glycoprotein that functions as an adhesion molecule and plays an important role in regulating cell adhesion and signaling pathways in cancer." (PMID 39911266, 2025). "This study aims to screen and explore novel sdAbs targeting EpCAM for cancer therapy." (PMID 40017594, 2025). "EpCAM and its close relative Trop2 are well-known cell surface markers of carcinoma, but their potential role in cancer metastasis remains unclear." (PMID 39572744, 2025). "Utilizing multiple conjugates against antigens expressed on differentiated PC and PCSC-like cells, such as CD44 and EpCAM, could be an effective method to eradicate residual cancer cells in heterogeneous tumors." (PMID 39846613, 2025). "Targeting EpCAM-expressing cancer cells with NIR-PIT could offer an effective therapeutic approach in appropriate cancers." (PMID 40792441, 2025). "Since EpCAM is upregulated in cancer cells preceding the epithelial-mesenchymal transition and metastasis, it is not unexpected that both hilar and mediastinal LNs would have cancer cells and therefore high EpCAM fluorescence." (PMID 41087662, 2025). "Cancer cell membrane-coated nanoparticles exploit homotypic targeting mechanisms mediated by surface adhesion molecules including N-cadherin, galectin-3, and epithelial cell adhesion molecule (EpCAM)." (PMID 41155895, 2025). "Hence, our study provides compelling evidence that targeting EpCAM for cancer treatment and demonstrates that the anti-EpCAM sdAbs are potential therapeutics for cancer treatment." (PMID 40017594, 2025). "Furthermore, binding of the five anti-EpCAM sdAbs to the three cancer cell lines DU145, PC3 and MCF-7 was tested by flow cytometric analysis, and 293T and 3T3 cells were included as negative controls." (PMID 40017594, 2025). "One may also reasonably predict that cancer cells can modulate this EpCAM-Trop2 system, resulting in more plasticity during various phases of cancer development." (PMID 39572744, 2025). "Besides, membrane‐specific protein Na+/K+‐ATPase, cancer cell membrane‐specific protein N‐Cadherin, E‐Cadherin, EpCAM were identified in CM and CMGCL." (PMID 39632613, 2025). "We reasoned that immunotherapy with EpCAM-ReTARGTPRIFNαR149A could be an attractive treatment option for this highly malignant cancer type." (PMID 40243928, 2025). "Several anti-EpCAM mAbs have been clinically tested for cancer therapy." (PMID 40017594, 2025). "We further evaluated the binding capability of EpCAM mAb to different human cancer cells." (PMID 40057807, 2025). "EpCAM is expressed in most cancers and reportedly exerts diverse biological functions." (PMID 40699639, 2025). "Interestingly, some patients in other cancer cohorts presented increased signals for EpCAM protein and EpCAM mRNA relative to those in the healthy cohort." (PMID 39556692, 2025). "We also examined the expression of ESCC cancer marker genes EPCAM and SFN in two cell populations." (PMID 40244296, 2025). "Notable exosomal proteins, such as the epidermal growth factor receptor (EGFR) and epithelial cell adhesion molecule (EpCAM), play significant roles in cancer progression through mechanisms including angiogenesis, proliferation, metastasis, and treatment resistance." (PMID 40317075, 2025). "However, compared to EpCAM-ReTARGTPR, this showed only marginal enhanced capacity to induce cancer cell lysis." (PMID 40243928, 2025). "Several anti-EpCAM mAbs were tested clinically for the treatment of different cancers." (PMID 40017594, 2025). "In addition, it was reported that EpCAM promoted cancer cell proliferation by its intracellular domain generated by TACE and PS-2." (PMID 40017594, 2025). "We confirmed EpCAM expression in cancer cells freshly derived from an MCC patient." (PMID 40243928, 2025).